TMUB1 (transmembrane and ubiquitin like domain containing 1)
Description:
Involved in sterol-regulated ubiquitination and degradation of HMG-CoA reductase HMGCR. Involved in positive regulation of AMPA-selective glutamate receptor GRIA2 recycling to the cell surface (By similarity). Acts as a negative regulator of hepatocyte growth during regeneration (By similarity). [iHOPS]: May contribute to the regulation of translation during cell-cycle progression. May contribute to the regulation of cell proliferation (By similarity). May be involved in centrosome assembly. Modulates stabilization and nucleolar localization of tumor suppressor CDKN2A and enhances association between CDKN2A and NPM1 (By similarity).
Synonyms: DULP; C7orf21; HOPS; SB144
Tractability: Antibody: UniProt places it where antibodies can reach, with medium confidence; UniProt predicts a signal peptide or a membrane-spanning region; its Gene Ontology location is reachable by antibodies, with medium confidence. PROTAC: ubiquitination databases record sites on it; its protein half-life has been measured.
Gene: Protein-coding gene on chromosome 7 (151,081,082 to 151,083,514, reverse strand). Ensembl gene ENSG00000164897.
Subcellular location: Membrane; Postsynaptic cell membrane; Recycling endosome; Cytoplasm; Nucleus; Nucleus, nucleolus; Cytoplasm (iHOPS); Cytoplasm, cytoskeleton, microtubule organizing center, centrosome
Subcellular location (Human Protein Atlas): Nucleoplasm; Cytosol
Gene Ontology:
Molecular function: protein binding
Biological process: ERAD pathway
Cellular component: cytoplasm; membrane; nucleus; postsynaptic membrane; recycling endosome; centrosome; nucleolus
Genetic constraint (gnomAD): Loss-of-function variants: 9 observed, 10.46 expected, observed/expected ratio (o/e) 0.86, 90% interval 0.52 to 1.49. The upper end of that interval is the gene's LOEUF score, 1.49, which puts it in group 6 of 6, group 1 being the genes least tolerant of losing a copy. Missense variants: 309 observed, 268.54 expected, observed/expected ratio (o/e) 1.15, 90% interval 1.05 to 1.26. Synonymous variants: 155 observed, 129.44 expected, observed/expected ratio (o/e) 1.2, 90% interval 1.05 to 1.37.
Homologues: Orthologues: chimpanzee TMUB1 (100% identical), macaque TMUB1 (98% identical), dog TMUB1 (94% identical), rabbit TMUB1 (92% identical), pig TMUB1 (91% identical), guinea pig TMUB1 (91% identical), rat Tmub1 (90% identical), mouse Tmub1 (57% identical), zebrafish tmub1 (48% identical), Caenorhabditis elegans B0303.4 (26% identical). Paralogues in human: TMUB2 (40% identical).
Diseases named in the same sentence as TMUB1 in open-access papers:
TMUB1 is named in the same sentence as 31 diseases in open-access papers, as found by Europe PMC text mining. Sharing a sentence is not in itself a finding about the gene and the disease. The quoted sentences say what the papers report.
hepatoma (3 papers, 2018 to 2023). "A recent study reported that TMUB1 can promote hepatoma cell apoptosis by enhancing the ubiquitination and degradation of the p63 protein." (PMID 36918802, 2023). "Moreover, TMUB1 promotes apoptosis by interacting with tumor protein 63 in hepatocellular carcinoma cells." (PMID 37249279, 2023). "TMUB1 is overexpressed in hepatoma cells and plays a negative regulatory role in the process of hepatocyte proliferation." (PMID 29967478, 2018).
colorectal cancer (2 papers, 2022 to 2023). A primary or metastatic malignant neoplasm that affects the colon or rectum. "We compared various colorectal cancer cell lines with normal intestinal cells and detected their mRNA expression levels to verify the TMUB1 expression level." (PMID 38025742, 2023). "It was also reported higher TMUB1 levels in cancerous tissue (colorectal cancer, stomach cancer, and oesophageal cancer) compared with healthy tissues of the digestive system." (PMID 38025742, 2023). "Higher TMUB1 expression levels were reported in human colorectal cancer (SW480, RKO, LoVo, and HT29) cells compared with that of the normal (NCM460) cells." (PMID 38025742, 2023). "However, only a few reports on the clinical significance of TMUB1 in colorectal cancer (CRC) exist." (PMID 35928927, 2022). "However, the expression of TMUB1 and its potential prognostic impact on colorectal cancer (CRC) has not yet been explored." (PMID 35928927, 2022).
abortion (1 paper, 2023). the ending of pregnancy by removing a fetus or embryo before it can survive outside the uterus. "Taken together, we confirm that TMUB1 induces apoptosis and activates the NF‐κB pathway to respond to inflammation in the occurrence of abortion." (PMID 37249279, 2023). "Then, the trophoblast cells and mouse models induced by LPS were used to explore the possible role of TMUB1 in abortion." (PMID 37249279, 2023). "Our results indicate that transmembrane and ubiquitin‐like domain containing 1 (TMUB1) may involve in the modulation of apoptosis and nuclear factor‐κB (NF‐κB) pathway‐mediated inflammation in recurrent spontaneous abortion (RSA)." (PMID 37249279, 2023). "In this study, we found that TMUB1 silencing decreased the expression of inflammatory cytokines in LPS‐activated trophoblast cells, indicating the facilitating role of TMUB1 in the inflammatory response during the development of abortion." (PMID 37249279, 2023). "Here, we suggested that TMUB1 silencing significantly suppressed the phosphorylation of IKKα/β and p65, indicating that TMUB1 might play an important role in abortion through NF‐κB pathway‐mediated inflammation." (PMID 37249279, 2023). "Based on RNA sequencing analysis that TMUB1 expression is significantly upregulated in the placental villous tissues of RSA patients compared with normal induced abortion patients, we guessed that recurrent miscarriages could be affected by TMUB1." (PMID 37249279, 2023).
Alzheimer disease (1 paper, 2022). A progressive, neurodegenerative disease characterized by loss of function and death of nerve cells in several areas of the brain leading to loss of cognitive function such as memory and language. "In recent research, hypoxia-induced miR-210 was shown to target synaptic function genes (GRINA, TMUB1, and AP2S1), plasticity genes (ACTB), Alzheimer’s disease genes (APOE), and genes implicated in MAPK/VEGF and OXPHOS signaling pathways." (PMID 35626359, 2022).
astrocytoma (1 paper, 2023). "We also compared TMUB1 expression in different glioma subtypes, including glioblastoma, astrocytoma, oligoastrocytoma, and oligodendroglioma." (PMID 38148953, 2023).
bladder cancer (1 paper, 2023). "The following TMUB1-related signalling pathways were identified by GSEA through comparative differential gene analysis: the insulin pathway, bladder cancer, glutathione metabolism, deoxyribonucleic acid (DNA) methylation, signalling by notch, and cell cycle checkpoints." (PMID 38025742, 2023).
breast carcinoma (1 paper, 2022). "Collectively, these results suggest that the TMUB1–PD-L1 axis is involved in breast cancer and gastric cancer tumorigenesis, highlighting the potential of utilizing this axis as a therapeutic target in the treatment of breast and gastric cancers." (PMID 36376293, 2022). "Further, TMUB1/STT3A/HUWE1 expression in breast cancer tumors was assessed using RT-qPCR." (PMID 36376293, 2022). "Change of TMUB1 protein level did not affect the cell proliferation for human breast cancer MDA-MB-231 cells, mouse breast cancer 4T1, EO771 cells, and gastric cancer MFC cells." (PMID 36376293, 2022). "Although TMUB1 does not appear to serve the same role in breast cancer cells due to differences in cell type or tumor selectivity." (PMID 36376293, 2022). "Changes in TMUB1 levels in breast cancer cells did not affect the RNA levels of PD-L1." (PMID 36376293, 2022). "Moreover, upregulation of both PD-L1 and TMUB1 was observed in breast cancer tumors compared to the corresponding adjacent non-malignant tissues." (PMID 36376293, 2022).
cholangiocarcinoma (1 paper, 2023). A carcinoma that arises from the intrahepatic biliary tree (intrahepatic cholangiocarcinoma) or from the junction, or adjacent to the junction, of the right and left hepatic ducts (hilar cholangiocarcinoma). "Among the 33 tumor types, TMUB1 was significantly overexpressed in 23 tumors, particularly in gastrointestinal tumors (cholangiocarcinoma, colon adenocarcinoma, oesophageal carcinoma, liver hepatocellular carcinoma, rectum adenocarcinoma, and stomach adenocarcinoma)." (PMID 38025742, 2023).
colon cancer (1 paper, 2023). "The degree of TMUB1 immune infiltration in colon cancer was examined, and it was discovered that TMUB1 was associated with a variety of immune cells." (PMID 38025742, 2023). "ROC analysis of TMUB1 expression may be a good diagnostic marker in colon cancer with an AUC of over 0.8." (PMID 38025742, 2023). "However, TMUB1 was reported to be a poor risk factor for colon cancer in our study." (PMID 38025742, 2023). "Particularly, TMUB1 expression was significantly higher in colon cancer tumors than in pericancerous tissues and in paired tumors than in normal tissues (N = 41)." (PMID 38025742, 2023). "Based on the findings from 10 paired colon cancer tissues, it was reported that TMUB1 expression in cancer tissues was higher than that in the adjacent tissues." (PMID 38025742, 2023). "We reported the expression level of TMUB1 in colon cancer and analyzed its potential prognostic value in colon cancer through the bioinformatics analysis and preliminary experimental studies." (PMID 38025742, 2023). "A poor prognosis was observed in colon cancer patients with a high TMUB1 expression than in those with a low TMUB1 expression." (PMID 38025742, 2023). "Herein, we reported the expression level of TMUB1 in colon cancer and analyzed its potential prognostic value in colon cancer through the bioinformatics analysis and preliminary experimental studies." (PMID 38025742, 2023). "TMUB1 is a promising prognostic marker for colon cancer based on its significant up-regulation in COAD, high diagnostic properties, and poor prognosis." (PMID 38025742, 2023). "In the HPA database, deeper immunohistochemical staining of cancer tissues compared with normal tissues was observed, suggesting that TMUB1 was significantly overexpressed in colon cancer tissues." (PMID 38025742, 2023). "Low-level methylation helps detect early precancerous lesions (Witte, Plass & Gerhauser, 2014), thereby indicating that TMUB1 has the potential to be used as a biomarker for the early diagnosis and treatment of colon cancer." (PMID 38025742, 2023). "The GEO database data sets (GSE9348, GSE23878, GSE47756, and GSE83889) revealed that TMUB1 expression in colon cancer was significantly higher than that in normal tissues." (PMID 38025742, 2023). "Using R language, the expression level of 33 cancer spectrum TMUB1 was analyzed by the public database TCGA, GEO and HPA, the differential expressed gene (DEG) screening and protein interaction (PPI) network was constructed, and the differential genes of TMUB1 in colon cancer were identified." (PMID 38025742, 2023). "Through the bioinformatics analysis of multiple databases and preliminary experimental studies, we found that the expression of TMUB1 was significantly increased in colon cancer tumors, and was correlated with the clinical N stage, pathological grade, lymphatic metastasis and BMI of colon cancer." (PMID 38025742, 2023). "However, research on the biological function of TMUB1 is warranted, and its role in terms of the tumor and mechanism in colon cancer requires further study." (PMID 38025742, 2023). "Further analysis showed that TMUB1 expression was significantly increased in colon cancer tumors." (PMID 38025742, 2023). "The HPA database revealed that TMUB1 was significantly overexpressed in colon cancer tissues." (PMID 38025742, 2023). "TMUB1 may have great potential as a tumor marker for diagnosing colon cancer." (PMID 38025742, 2023). "TMUB1 may be involved in the regulation of the malignant progression of colon cancer." (PMID 38025742, 2023).
colon cancer (continued). "The high expression of TMUB1 is a negative prognostic factor for colon cancer patients." (PMID 38025742, 2023).
esophageal tumors (1 paper, 2022). "Transmembrane and ubiquitin-like domain-containing protein 1 (TMUB1) is overexpressed in a large number of liver and esophageal tumors." (PMID 35928927, 2022). "Moreover, TMUB1 is overexpressed in a large number of CNS, liver, and esophageal tumors." (PMID 35928927, 2022).
gastric cancer (1 paper, 2022). A primary or metastatic malignant neoplasm involving the stomach. "A similar series of analyses were performed for the individuals with gastric cancer, and the same conclusion was reached, i.e., higher TMUB1 levels were associated with higher PD-L1 levels and worse clinical outcomes in the patients with gastric carcinoma." (PMID 36376293, 2022).
glioblastoma (1 paper, 2023). The most malignant astrocytic tumor (WHO grade IV). "Our analysis revealed significantly higher TMUB1 levels in glioblastoma compared to other subtypes, suggesting its potential relevance in the aggressiveness of glioma." (PMID 38148953, 2023).
glioma (1 paper, 2023). A benign or malignant brain and spinal cord tumor that arises from glial cells (astrocytes, oligodendrocytes, ependymal cells). "The precise molecular pathways underlying TMUB1's impact on glioma patient survival remain a subject of interest for future research." (PMID 38148953, 2023). "In conclusion, our study unveils the multifaceted roles of TMUB1 in glioma, establishing it as a novel diagnostic biomarker and a robust prognostic indicator." (PMID 38148953, 2023). "This study contributes valuable insights into the multifaceted role of TMUB1 in glioma pathogenesis and its potential as a diagnostic and therapeutic target." (PMID 38148953, 2023). "In this study, we explored the multifaceted role of transmembrane and ubiquitin-like domain-containing 1 (TMUB1) in glioma, shedding light on its potential as a diagnostic biomarker, a prognostic indicator, and even a therapeutic target." (PMID 38148953, 2023). "The results demonstrated a significant association (P = 0.001) between higher WHO grades (grade III and grade IV) and increased TMUB1 expression, indicating that more advanced glioma grades were associated with elevated TMUB1 mRNA levels." (PMID 38148953, 2023). "Our investigation revealed the clinical relevance of TMUB1 as a potential diagnostic and prognostic marker in glioma, emphasizing its critical role as a prognostic indicator." (PMID 38148953, 2023). "High TMUB1 expression is consistently linked to worse overall survival, supporting its potential utility in risk stratification and treatment decision-making for glioma patients." (PMID 38148953, 2023). "Additionally, the underlying mechanisms by which TMUB1 influences glioma progression and immune responses require further elucidation." (PMID 38148953, 2023). "Moreover, high TMUB1 mRNA levels were associated with a noteworthy HR of 2.389 (95% CI: 1.504-3.796, P < 0.001), underlining the robust prognostic significance of elevated TMUB1 expression in gliomas." (PMID 38148953, 2023). "The significant upregulation of TMUB1 in glioma tissues compared to normal brain tissues highlights its potential as a diagnostic marker." (PMID 38148953, 2023). "Through a comprehensive analysis of clinical data, functional experiments, and immune infiltration assessments, we shed light on the multifaceted involvement of TMUB1 in glioma progression and patient outcomes." (PMID 38148953, 2023). "Functional experiments provided mechanistic insights into TMUB1's oncogenic role, and our analysis unveiled correlations between TMUB1 expression and immune cell infiltration in the glioma microenvironment." (PMID 38148953, 2023). "Our data revealed that TMUB1 levels were significantly higher in glioma tissues from patients who experienced disease progression, suggesting its involvement in glioma advancement." (PMID 38148953, 2023). "Following the successful knockdown of TMUB1, we proceeded to evaluate the impact of TMUB1 silencing on glioma cell growth using MTT experiments." (PMID 38148953, 2023). "Among the 109 glioma patients, 53 had low TMUB1 expression, and 56 had high TMUB1 expression according to the median cut-off value of mRNA level." (PMID 38148953, 2023). "To investigate the functional impact of TMUB1 on glioma cell growth, we employed a knockdown approach and assessed its effects on cellular proliferation." (PMID 38148953, 2023). "While our study contributes significantly to understanding the role of TMUB1 in glioma, several limitations merit consideration." (PMID 38148953, 2023). "Correlations with immune cell infiltration suggest TMUB1's involvement in the complex immune landscape of glioma." (PMID 38148953, 2023). "To investigate the mRNA levels of TMUB1 in glioma, we analyzed TCGA cohort of glioma tissues and compared them to normal brain tissues." (PMID 38148953, 2023). "Our results revealed that TMUB1 expression was elevated in glioma tissues compared to normal brain tissues." (PMID 38148953, 2023).